SLC4A7 (solute carrier family 4 member 7)
Diseases named in the same sentence as SLC4A7 in open-access papers (continued):
Sharing a sentence is not in itself a finding about the gene and the disease.
invasive breast carcinoma (1 paper, 2016). A carcinoma that infiltrates the breast parenchyma. "We have also shown for the first time that seven of the known invasive breast cancer predisposition loci not previously shown to be associated with DCIS have comparable ORs for IDC and DCIS: rs4973768 (SLC4A7), rs3821902 (ATXN7), rs10995190 (ZNF365), rs554219 (CCND1), rs3757318 and rs2046210 (ESR1)." (PMID 26884359, 2016).
metastatic disease (1 paper, 2020). "The Na+–HCO3 cotransporter (SLC4A7, NBCn1) has also been considered to be the main mechanism of H+ extrusion, pHi elevation and CPR in BC, being actively involved in both BC carcinogenesis and in metastatic disease." (PMID 33050492, 2020).
retinal degeneration (1 paper, 2024). Degeneration of the retina. "The results of our investigation provide initial insights into the influence of slc4a7 on visual health and retinal development in zebrafish, highlighting a range of retinal degeneration phenotypes evident between 3 and 5 dpf." (PMID 39273559, 2024). "We then examined slc4a7-mediated downstream targets that could account for the aberrant photoreceptors, RPE, and amacrine cells during the pathogenesis of retinal degeneration." (PMID 39273559, 2024).
tuberculosis (1 paper, 2025). A chronic, recurrent infection caused by the bacterium Mycobacterium tuberculosis. "Notably, this research represents the first comprehensive identification of significant differential expression patterns of FHIT, MAN1C1, SLC4A7, NT5E, and other genes in patients with tuberculosis (TB)." (PMID 40524207, 2025).
cancer (27 papers, 2013 to 2025). A tumor composed of atypical neoplastic, often pleomorphic cells that invade other tissues. "SLC4A7 is revealed to upregulate in the carcinoma cell line in the presence of the MCF-7 Nt-truncated ErbB2 receptor (NErbB2)." (PMID 37894847, 2023). "On the other hand, MYO5A and SLC4A7 were also reported to promote proliferation, invasion, metastasis and apoptosis resistance in many cancers." (PMID 34336638, 2021). "The strongest evidence for involvement of HCO−3 transporters in human cancer has been provided for NBCn1 (SLC4A7) and DRA (SLC26A3)." (PMID 24795638, 2014). "Since SLC4A7 is also expressed in the smooth muscle and endothelial cells of the vascular wall and is important for maintaining vasomotor responsiveness and possibly arterial structure, it is conceivable that SLC4A7 may also in part affect cancer development by modifying blood perfusion of tumors." (PMID 24795638, 2014). "Two related transcription factors with known roles in cancer, Sp1 and KLF4, bind to the SLC4A7 promoter, exerting opposite functions: Sp1 represses and KLF4 activates SLC4A7 transcription." (PMID 24795638, 2014). "These transporters, including the Na+/H+ exchanger NHE1 (SLC9A1) and the Na+, HCO3- cotransporters NBCn1 (SLC4A7) and NBCe2 (SLC4A5) confer additional advantages to the cancer cells, including stimulation of proliferation, survival, and invasiveness, leading to increased tumor growth and metastasis." (PMID 32457840, 2020). "Firstly, the mRNA expression levels of most of the SLC4 and SLC26 family members differ widely between normal and cancer tissue, with a clear trend toward upregulation of SLC4A3, SLC4A7, and SLC26A6, and downregulation of SLC4A1 in cancer compared to normal tissue." (PMID 24795638, 2014). "Of note, the TCGA data show no consistent upregulation of SLC4A7 mRNA levels in cancer, which is at variance with the pattern indicated from protein level data in." (PMID 24795638, 2014).
tumor (22 papers, 2014 to 2026). "Both in vivo and in vitro data demonstrate that the alkalinization of the TME induced by Slc4a7 knockout enhances the infiltration and function of cytotoxic T cells, significantly inhibiting tumor growth." (PMID 42088432, 2026). "Notable candidate genes included ANKH (12 associated SNPs), EIF6 (11 SNPs), and SLC4A7, DLG2, and FBXL7, which are widely implicated in cellular inflammation, immune response, and tumor development." (PMID 40427243, 2025). "The result showed a significant positive correlation between SLC4A7 level and lactate abundance (Spearman’s correlation = 0.38, p = 7e-14), indicating the importance of SLC4A7 to cellular pH homeostasis in tumor cells." (PMID 35440542, 2022). "Intriguingly, the EVs secreted by invasive tumoroids (3D d10‐d14) contained several unique proteins promoting tumour growth and invasion, for example, SLC4A7, SLC12A2, FABP5, PRDX1, CD59 and CD73, showing that specific oncogenic signals are loaded in EVs upon invasion." (PMID 38938900, 2023). "EVs secreted by invasive tumoroids (3D d10‐d14) included proteins promoting tumour growth (solute carrier family 12 member 2, SLC12A2; sodium bicarbonate cotransporter 3, SLC4A7), tumour invasion (fatty acid binding protein 5, FABP5) and immunosuppression (cluster of differentiation 73, CD73)." (PMID 38938900, 2023). "Mediators of increased acid extrusion in tumor cells include the Na+/H+ exchanger NHE1 (SLC9A1), the Na+,HCO3− cotransporter NBCn1 (SLC4A7), the lactate,H+ cotransporters of the monocarboxylate transporter family, MCT1 and MCT4 (SLC16A1 and −3), and, in some cells, V-type H+-ATPases." (PMID 27266704, 2016).
cardiovascular disease (1 paper, 2020). "The life-extending allele of the majority of the loci is associated with a reduction in cardiovascular disease phenotypes, including SNPs near the ageing loci SLC4A7, FGD6, and LINC02513 discovered in this study." (PMID 32678081, 2020).
SLC4A7 also shares sentences with these, for which no sentence is quoted: lung carcinoma (5 papers); colon cancer (2); glioblastoma (2); neurodegenerative disease (2); pancreatic cancer (2); rheumatoid arthritis (2); adenoma (1); Alzheimer disease (1); Anxiety (1); bacterial infection (1); benign breast disease (1); bladder cancer (1); breast (1); cardiac hypertrophy (1); cognitive decline (1); dependence (1); epilepsy (1); heart disease (1); Hydrocephalus (1); hyperlipidemia (1); infection (1); infectious disease (1); invasive ductal carcinomas (1); invasive lobular carcinomas (1); ischemic heart disease (1); lung adenocarcinoma (1); lymph node metastasis (1); neurological diseases (1); neurotoxicity (1); non-small cell lung carcinoma (1).
A further 11 diseases each share a sentence with SLC4A7 in 1 paper.